PSMB8 (proteasome 20S subunit beta 8)
Description:
The proteasome is a multicatalytic proteinase complex which is characterized by its ability to cleave peptides with Arg, Phe, Tyr, Leu, and Glu adjacent to the leaving group at neutral or slightly basic pH. The proteasome has an ATP-dependent proteolytic activity. This subunit is involved in antigen processing to generate class I binding peptides. Replacement of PSMB5 by PSMB8 increases the capacity of the immunoproteasome to cleave model peptides after hydrophobic and basic residues. Involved in the generation of spliced peptides resulting from the ligation of two separate proteasomal cleavage products that are not contiguous in the parental protein. Acts as a major component of interferon gamma-induced sensitivity. Plays a key role in apoptosis via the degradation of the apoptotic inhibitor MCL1. May be involved in the inflammatory response pathway. In cancer cells, substitution of isoform 1 (E2) by isoform 2 (E1) results in immunoproteasome deficiency. Required for the differentiation of preadipocytes into adipocytes.
Synonyms: LMP7; PSMB5i; RING10; D6S216E; beta5i; ALDD; D6S216; JMP; NKJO; PRAAS1
Tractability: Small molecule: an approved drug acts on it; a structure with a bound ligand is known; a high-quality ligand is known; it belongs to a druggable protein family. PROTAC: ubiquitination databases record sites on it; its protein half-life has been measured; a small molecule that binds it is known.
Target class: Threonine protease; Protease; Threonine protease T1A subfamily; Threonine protease PBT clan; Enzyme
Chemical probes: ONX-0914, PR-924
Gene: Protein-coding gene on chromosome 6 (32,840,717 to 32,844,679, reverse strand). Ensembl gene ENSG00000204264.
Subcellular location: Cytoplasm; Nucleus
Subcellular location (Human Protein Atlas): Vesicles; Cytokinetic bridge
Pathways (Reactome):
Immune System: Antigen processing: Ub, ATP-independent proteasomal degradation; Cross-presentation of soluble exogenous antigens (endosomes); ER-Phagosome pathway; Interferon alpha/beta signaling
Metabolism of proteins: Proteasome assembly
Gene Ontology:
Molecular function: protein binding; endopeptidase activity; threonine-type endopeptidase activity
Biological process: fat cell differentiation; proteasome-mediated ubiquitin-dependent protein catabolic process; CD8-positive, alpha-beta T cell homeostasis; immune system process; negative regulation of regulatory T cell differentiation; positive regulation of interleukin-2 production; positive regulation of tumor necrosis factor production; positive regulation of type II interferon production; proteasomal protein catabolic process; response to type II interferon; T-helper 1 cell differentiation; T-helper 17 cell differentiation; protein catabolic process
Cellular component: extracellular exosome; proteasome complex; cytosol; nucleoplasm; nucleus; proteasome core complex; proteasome core complex, beta-subunit complex; spermatoproteasome complex; cytoplasm
Genetic constraint (gnomAD): Loss-of-function variants: 20 observed, 34.24 expected, observed/expected ratio (o/e) 0.58, 90% interval 0.41 to 0.85. The upper end of that interval is the gene's LOEUF score, 0.85, which puts it in group 3 of 6, group 1 being the genes least tolerant of losing a copy. Missense variants: 342 observed, 387.16 expected, observed/expected ratio (o/e) 0.88, 90% interval 0.81 to 0.97. Synonymous variants: 131 observed, 144.59 expected, observed/expected ratio (o/e) 0.91, 90% interval 0.79 to 1.05.
Homologues: Orthologues: chimpanzee PSMB8 (99% identical), pig PSMB8 (90% identical), rabbit PSMB8 (89% identical), rat Psmb8 (89% identical), mouse Psmb8 (88% identical), guinea pig PSMB8 (87% identical), tropical clawed frog psmb8 (68% identical), zebrafish psmb8a (67% identical), Caenorhabditis elegans pbs-1 (22% identical), Drosophila melanogaster Prosbeta1 (22% identical). Paralogues in human: PSMB5 (56% identical), PSMB11 (46% identical), PSMB6 (25% identical), PSMB9 (24% identical), PSMB10 (21% identical), PSMB7 (21% identical), PSMB1 (18% identical), PSMB3 (18% identical), PSMB4 (18% identical), PSMA2 (17% identical), PSMA4 (16% identical), PSMB2 (16% identical), and 6 more.
Diseases named in the same sentence as PSMB8 in open-access papers:
PSMB8 is named in the same sentence as 224 diseases in open-access papers, as found by Europe PMC text mining. Sharing a sentence is not in itself a finding about the gene and the disease. The quoted sentences say what the papers report.
melanoma (24 papers, 2010 to 2025). A malignant, usually aggressive tumor composed of atypical, neoplastic melanocytes. "In lung cancer, as in melanoma, higher expression of PSMB8 is associated with a more favorable prognosis, perhaps through increased immune surveillance." (PMID 34944095, 2021). "Immunoproteasome expression was evaluated as a predictive marker for immune checkpoint blockade therapy in melanoma, with high expression of PSMB8 and PSMB9 associated with better response to anti-PD-1 and anti-CTLA-4 treatment." (PMID 34944095, 2021). "However, within the 26S proteasome, large variability was observed for the protein complex subunits PSMB9 and PSMB8 of the immunoproteasome, the expression of which is associated with immune response to ICBs in melanoma." (PMID 38047086, 2023). "PSMB8 deficiency has been shown to promote tumor growth in a mouse model of melanoma." (PMID 34944095, 2021). "For instance, NSCLC, melanoma, as well as muscle-invasive bladder, breast and thymic cancers expressing high levels of PSMB8, 9 and 10 were shown to respond better to the treatment." (PMID 40698074, 2025). "PSMB8/9 expression linked to improved survival and checkpoint response, outperforming TMB in melanoma; functional link to enhanced TIL recognition." (PMID 41293269, 2025). "In breast cancer, NSCLC, bladder urothelial cancer, sarcoma, mesothelioma, melanoma and thymic cancer, elevated levels of PSMB8, 9 or 10 mRNA correlate with improved survival." (PMID 40698074, 2025). "Here it should be mentioned that upregulated PSMB8/9 expression correlated with increased efficacy of immune checkpoint inhibitors in melanoma and lower-grade glioma." (PMID 38774235, 2024). "PSMB8/9 overexpression indicated a good prognosis in patients with melanoma and a good response to immune-checkpoint inhibitors." (PMID 36268281, 2022). "In support of this, overexpression of PSMB8 in melanoma cell lines increased IFN-γ secretion, leading to efficient killing of tumor cells by tumor infiltrating CTLs." (PMID 34944095, 2021). "Finally, PSMB8 KO mice exhibit depleted Th1 CD4 T cells within melanoma tumors, which was shown to allow for faster progression." (PMID 40698074, 2025). "Besides, the aberrant expression of PSMB8 was observed in various malignancies, such as malignant melanoma, breast cancer, gastric cancer, esophageal squamous cell carcinoma, colorectal cancer and cervical cancer 72, 78-84." (PMID 35693739, 2022). "The expression of SLAMF8 and PSMB8 could predict the efficacy of immune checkpoint inhibitor immunotherapy in gastrointestinal cancer and melanoma." (PMID 36225561, 2022). "PSMB8 and 9 are also overexpressed in lung, pancreatic, stomach, colon, prostate, thyroid, liver, uterine, cervical, testicular, ovarian and rectal cancers, as well as in diffuse large B cell lymphoma, acute myeloid leukemia, glioma, glioblastoma, cholangioma and melanoma." (PMID 40698074, 2025). "To test this hypothesis, we utilized HLA peptidomics to analyze the changes in the HLA peptide repertoire of melanoma cells due to PSMB8 and PSMB9 overexpression and determined the effects of these changes on the reactivity of patient infiltrating tumor lymphocytes (TILs)." (PMID 32060274, 2020). "We describe here that the overexpression of PSMB8 and PSMB9, two major components of the immunoproteasome, is predictive of better survival and improved response to immune-checkpoint inhibitors of melanoma patients." (PMID 32060274, 2020). "This is the first report to establish the association between the overexpression of immunoproteasome subunits PSMB8 and PSMB9 and improved survival and enhanced response to immune-checkpoint inhibitors (both anti-CTLA4 and anti-PD1) in melanoma patients." (PMID 32060274, 2020). "To assess the relationship between the expression levels of immunoproteasome subunits PSMB8 and PSMB9 and melanoma patient survival, we analyzed data from TCGA of 472 melanoma patients for whom RNA-seq data and patient outcome were available." (PMID 32060274, 2020).
melanoma (continued). "Because these roles of LMP7, we knocked down the expression of the corresponding gene, PSMB8, by siRNA and confirmed knockdown at the protein level in melanoma cell lines." (PMID 26885372, 2016). "Similar results have been observed in melanoma and triple negative breast cancer that patients with accumulated PSMB8 expression gained prolonged survival time." (PMID 40334200, 2025). "Importantly, we find that PSMB8 and PSMB9 expression levels are much stronger predictors of melanoma patientsʼ immune response to checkpoint inhibitors than the tumors’ mutational burden." (PMID 32060274, 2020). "Here, the authors demonstrate that a high expression of the two major components of the immunoproteasome, PSMB8 and PSMB9, modulates the production of HLA peptides and it is predictive of better survival and improved response to immune-checkpoint inhibitors of melanoma patients." (PMID 32060274, 2020). "To test our hypothesis that overexpression of IP subunits derives alternative, more immunogenic peptides, we overexpressed both PSMB8 and PSMB9 (OE) or a vector control (EV) in three different melanoma cell lines (108T, 12T and A375)." (PMID 32060274, 2020). "The insights gathered through these analyses suggest that the expression levels of immunoproteasome subunits PSMB8 and PSMB9 can serve as biomarkers for predicting survival of melanoma patients and for identifying patients likely to favorably respond to immune-checkpoint inhibitors." (PMID 32060274, 2020).
Nakajo-Nishimura syndrome (23 papers, 2013 to 2026). "Initially, mutations in PSMB8 were identified as the primary cause of Nakajo Nishimura syndrome, JMP syndrome, and CANDLE syndrome." (PMID 41466885, 2026). "A recently identified dysregulation of the IFN signalling pathway is also supported by genetic data demonstrating that mutations in PSMB8 cause CANDLE syndrome; all nine study patients had elevated, though variable, levels of IFNg inducible protein 10 (IP-10)." (PMID 41466885, 2026). "The mutation associated with CANDLE syndrome is in PSMB8 (proteasome subunit β type 8), which is activated by interferon γ and produces cytokines." (PMID 40660608, 2025). "The mutation associated with CANDLE syndrome is in PSMB8 (proteasome subunit β type 8), activated by interferon γ, and produces cytokines." (PMID 40660608, 2025). "Nakajo-Nishimura syndrome is a hereditary autoinflammatory disorder caused by an autosomal recessive homozygous mutation of the PSMB8 gene, which encodes the immunoproteasome subunit beta 5i." (PMID 37654638, 2023). "Genetic aberrations in the PSMB8 immunoproteasome gene have been associated with cancer and a wide range of immune and inflammatory diseases, e.g. Nakajo-Nishimura syndrome, CANDLE syndrome, and intestinal M. tuberculosis infection." (PMID 36123629, 2022). "Chronic atypical neutrophilic dermatosis with lipodystrophy and elevated temperature (CANDLE), formerly known as Nakajo–Nishimura syndrome, is another monogenic condition caused by the PSMB8 gene encoding for a protein of the proteasome." (PMID 35242725, 2022). "PSMB8 encodes for immunoproteasome subunit β5i and, together with other mutations of the immunoproteasome, are grouped within the proteosome-associated autoinflammatory syndromes (PRAASs)." (PMID 35242725, 2022). "Based on the clinical manifestations and the genomic mutation on PSMB8 gene, the diagnosis of Nakajo–Nishimura syndrome was made." (PMID 32513120, 2020). "Nakajo-Nishimura syndrome is a proteasome-associated autoinflammatory syndrome with a distinct homozygous mutation in the PSMB8 gene encoding an inducible β5i subunit of the immunoproteasome." (PMID 31143302, 2019). "Nakajo-Nishimura syndrome (NNS) is a proteasome -associated autoinflammatory syndrome (PRAAS) with a distinct homozygous mutation in the PSMB8 gene encoding an inducible β5i subunit of the immunoproteasome (iP)." (PMID 31143302, 2019). "The first gene mutations detected in patients with CANDLE syndrome were located in the gene PSMB8 (proteasome subunit, beta-type, 8) in chromosome 6p21.32, encoding for the β5i (i = inducible) subunit of the immunoproteasome." (PMID 28848544, 2017). "The CANDLE syndrome is caused, in the majority of cases, by homozygous mutations in PSMB8 gene, which encodes for a proteasome protein." (PMID 28421071, 2017). "The CANDLE syndrome is caused by homozygosity for mutations in the Proteasome (Prosome, Macropain) Subunit, Beta Type, 8 (PSMB8) gene that encodes for proteasomes that are responsible for the physiological degradation of proteins." (PMID 26711936, 2015). "Using genome-wide homozygosity mapping, a homozygous missense mutation (c.224C > T, Thr75Met) in the proteasome gene PSMB8 that encodes the β5i (LMP7) subunit was detected in two pedigrees from Portugal and Mexico with JMP syndrome." (PMID 24490108, 2013). "Genetic studies confirmed a homozygous nonsense mutation in PSMB8, a diagnostic of CANDLE syndrome." (PMID 40660608, 2025). "CANDLE syndrome (chronic atypical neutrophilic dermatosis with lipodystrophy and elevated temperature) is an autoinflammatory disorder characterized by recurrent fever, skin lesions, and other symptoms caused by a mutation in the PSMB8 gene." (PMID 40660608, 2025). "A genetic study showed a homozygous nonsense mutation in PSMB8 associated with CANDLE syndrome." (PMID 40660608, 2025).
Nakajo-Nishimura syndrome (continued). "In 2012, a genome-wide analysis of nine CANDLE syndrome affected patients in eight families suggested that mutations in PSMB8 gene may cause the CANDLE syndrome." (PMID 28421071, 2017). "The diagnosis of CANDLE syndrome was based on the typical clinical features of widespread annular violaceous skin lesions and the multisystemic inflammatory characteristics and had been confirmed by finding a homozygous mutation in PSMB8." (PMID 26137574, 2015). "A recent genome-wide analysis of nine affected patients in eight families suggests that mutations in PSMB8 may be the molecular basis of CANDLE syndrome." (PMID 24490108, 2013). "It has recently been shown that mutations and polymorphisms in the immunoproteasome catalytic subunit PSMB8 are associated with several inflammatory and autoinflammatory diseases including Nakajo-Nishimura syndrome, CANDLE syndrome, and intestinal M. tuberculosis infection." (PMID 24490108, 2013). "Nakajo-Nishimura syndrome (NNS) is an autosomal recessive heredity disorder, one of a spectrum of autoinflammatory diseases named proteasome-associated autoinflammatory syndrome (PRAAS) caused by mutations of PSMB8 gene." (PMID 32513120, 2020). "For instance, Nakajo-Nishimura syndrome (NNS), one of the interferonopathies caused by mutations in PSMB8, was previously studied using iPSC-based drug screening systems derived from NNS patients." (PMID 41026253, 2025). "CANDLE syndrome, also known as proteasome associated autoinflammatory syndrome (PRAAS), is an autosomal recessive interferonopathy caused by mutations in the PSMB8 (Proteasome 20S Subunit Beta 8) gene, which encodes the β5i subunit of the immunoproteasome." (PMID 38984133, 2024). "Genetic testing excluded Mediterranean fever and chronic atypical neutrophilic dermatosis with lipodystrophy and elevated temperature (CANDLE) syndrome caused by mutations in MEFV and PSMB8, respectively." (PMID 30804083, 2019). "The designation of PRAAS was first used when a case with compound heterozygous PSMB8 mutations was reported, and then was further applied for the generic name of JMP syndrome, NNS/JASL, and CANDLE syndrome." (PMID 31143302, 2019). "Recently, new mutations related to the CANDLE syndrome were identified in the PSMA3 gene coding α7, PSMB4 coding β7, and PSMB9 coding β1i as well as PSMB8 and proteasome maturation protein (POMP) genes from 8 patients." (PMID 29259686, 2016). "Mutations in PSMB8 were responsible for CANDLE, JMP, and Nakajo–Nishimura syndromes." (PMID 28848544, 2017). "Recent developments indicate that not all individuals affected by the CANDLE syndrome have PSMB8 mutations." (PMID 26711936, 2015). "Mutations have been discovered in PSMB8, whose gene product is a component of the immunoproteasome, in some, but not all patients, with CANDLE syndrome." (PMID 26137574, 2015).